ATM (ATM serine/threonine kinase)
Diseases named in the same sentence as ATM in open-access papers (continued):
Sharing a sentence is not in itself a finding about the gene and the disease.
pancreatic cancer (210 papers, 2009 to 2026). "The resulting splicing data have ultimately contributed to a tentative clinical classification based on the ClinGen Hereditary Breast, Ovarian and Pancreatic Cancer Variant Curation Expert Panel (HBOP VCEP) Specifications for ATM variants." (PMID 41596415, 2026). "Their research showed that partial or complete ATM deficiency interacts with the KRAS gene to promote highly metastatic pancreatic cancer and also leads to permanent DNA damage in precancerous lesions and primary tumors." (PMID 41155399, 2025). "Given the frequency of ATM variants, ATM PTVs would explain ~2% of pancreatic cancer cases (with potentially a higher proportion due to MSVs)." (PMID 39209703, 2024). "There is growing evidence that pathogenic ATM variants increase the risk of several tumor types, including melanoma, ovarian, and pancreatic cancer, among others." (PMID 39594770, 2024). "By age 80, the estimated cumulative risk of pancreatic cancer in ATM PTV carriers was 8% (2% to 15%) in males and 6% (1% to 10%) in females." (PMID 39209703, 2024). "The mutation in the ATM gene is associated with an increased risk of breast cancer; however, the data on the risk of pancreatic cancer in individuals with kindreds of pathogenic variations are limited." (PMID 39200847, 2024). "ATM has been established as a predisposition gene for multiple malignancies including breast and pancreatic cancer and melanoma." (PMID 38338943, 2024). "The overall relative risk of pancreatic cancer in patients with pathogenic ATM variants is 6.5 (95% CI: 4.5–9.5)." (PMID 39200847, 2024). "Given the significant biological roles of these genes, various studies have explored the efficacy of ATM inhibitors in ATM-deficient lung, prostate, and pancreatic cancer cells." (PMID 39421870, 2024). "In a study of 166 familial pancreatic cancer probands, 2.4% were carriers of the deleterious ATM variant." (PMID 36765737, 2023). "RNA sequencing was performed on ATM-knockdown pancreatic-cancer cells to elucidate the mechanism underlying the invlovement of ATM in pancreatic cancer." (PMID 37674118, 2023). "Three germline deleterious variations in cancer susceptibility genes, known as pancreatic cancer susceptibility genes (ATM, WRN, and PALB2), were identified in our study population." (PMID 37313463, 2023). "Genetic testing revealed the patient had a pathogenic variant in the ATM gene that is associated with an increased risk for pancreatic cancer development." (PMID 37684686, 2023). "In one study, the relative risk of pancreatic cancer was estimated to be 2.41 in patients carrying a monoallelic ATM germline variant." (PMID 38201484, 2023). "Protein‐truncating variants in three DNA damage repair genes (PALB2, BRCA2, and ATM) were associated with a significant risk of pancreatic cancer (p < 0.05), with odds ratio ranging from 5.03 to 10.03." (PMID 36999792, 2023). "Mutations in kinase ATM are the genetic defects in hereditary cancer-predisposing ataxia–telangiectasia syndrome and underline a sub-set of familial pancreatic cancers." (PMID 36975505, 2023). "PALB2, BRCA2, and ATM PGVs were associated with high risks for pancreatic cancer in the Chinese population." (PMID 36999792, 2023).
pancreatic cancer (continued). "Lastly, a patient with a recent episode of pancreatitis was diagnosed with pancreatic cancer after she filled out the questionnaire and was found to carry a pathogenic ATM variant." (PMID 36820377, 2023). "ATM germline PVs have been found to be associated with several types of cancer, especially breast and pancreatic cancer." (PMID 35008949, 2022). "Targeting ataxia telangiectasia mutated (ATM)—a kinase that plays a role in the DNA damage response to double stranded DNA breaks induced by radiotherapy—sensitizes pancreatic cancer to ICIs, providing a mechanistic link for this observed synergy." (PMID 36387071, 2022). "ATM mutations have been reported to occur in 2.4% of familial pancreatic cancer patients and 3-4% in a study with a population unselected for family history of cancer." (PMID 35228986, 2022). "Over the past few decades, associations between germline ATM pathogenic variants and cancer risk have been reported, particularly for breast and pancreatic cancers." (PMID 35008949, 2022). "Another analysis of individuals receiving germline MGP testing demonstrated that ATM PVs were associated with a high risk of pancreatic cancer with an OR of 4.21 (95%CI, 3.24–5.47; p < 0.0001)." (PMID 35008949, 2022). "Heterozygous carriers of ATM PVs are at increased risk of several types of cancer, including pancreatic cancer, and it is estimated that up to 3% of high-risk individuals who develop pancreatic cancer harbor an ATM PV." (PMID 35563100, 2022). "A case–control analysis identified association between ATM germline PVs and increased pancreatic cancer risk (2.3% of cases and 0.37% of controls; OR, 5.71; 95% CI, 4.38–7.33)." (PMID 35008949, 2022). "Although the lifetime risk for pancreatic cancer remains uncertain, the ATM pathogenic variant is associated with an increased risk of pancreatic cancer." (PMID 35163129, 2022). "Although germline variants in ATM are associated with increased risk of breast and pancreatic cancer, their association with esophagogastric cancer is less certain." (PMID 34251444, 2021). "Germline mutations associated with pancreatic cancer are ATM (2%–4%), BRCA1 (0%–1%), BRCA2 (8%–19%), CHEK2 (2%–9%), and PALB2 (3.1%–3.7%)." (PMID 33764904, 2021). "The ATM pathogenic germline variant is strongly associated with breast, ovarian, prostate, and pancreatic cancer." (PMID 34476650, 2021). "BRCA2 and ATM germline pathogenic variants are significantly more prevalent in familial pancreatic cancer patients." (PMID 34476650, 2021). "Jiao and colleagues whole-genome sequenced 23 cases of acinar cell carcinoma, a tumor type associated with a poor prognosis that accounts for approximately 2% of pancreatic cancer cases, and found one somatic ATM mutation (4%)." (PMID 31963441, 2020). "There was a significant association between ATM and the risk of pancreatic cancer (OR, 7.73; 95% CI, 3.10 to 19.33, P = 6.14E‐05)." (PMID 32255556, 2020). "In this review, we discuss the role of ATM in susceptibility to PDAC, as well as screening and early diagnosis of PDAC in heterozygous carriers of pathogenic germline variants in pancreatic cancer susceptibility genes, such as ATM." (PMID 31963441, 2020). "The patient (P89) carrying the pathogenic ATM variant c.3576G>A had pancreatic cancer at 66 years of age." (PMID 32957588, 2020). "Next-generation sequencing of familial pancreatic cancer (FPC) patients provided the first conclusive evidence that ATM was a pancreatic cancer susceptibility gene." (PMID 31963441, 2020).
pancreatic cancer (continued). "In one of the largest studies to date of 3030 pancreatic cancer patients, pathogenic germline ATM variants were identified in 69 patients (2.3%; 95% confidence interval (CI), 4.38–7.33), including 11 patients with FPC." (PMID 31963441, 2020). "Synthetic lethal interactions between ATM and ATR have also been observed, with ATM-deficient pancreatic cancer cell lines showing growth inhibition to ATR inhibitors." (PMID 31963441, 2020). "In this study, 11 out of 290 patients with PDAC had a pathogenic germline variant in a pancreatic cancer susceptibility gene, including three in ATM, one of which had a family history of FPC." (PMID 31963441, 2020). "Consistently, human and murine BAP1-deficient pancreatic cancer cell lines showed a pronounced sensitivity and activation of ATM/ATR kinases and H2A.XSer139 phosphorylation upon different means of DNA damage." (PMID 32541668, 2020). "ATM and its role in pancreatic cancer was recently reviewed and germline mutations in ATM have been associated with predisposition for several cancer forms including PrCa." (PMID 32183364, 2020). "Recent large-scale sequencing studies of pancreatic cancer patients have shown that pathogenic germline ATM variants are one of the most frequently identified germline alterations in pancreatic cancer patients." (PMID 31963441, 2020). "Of note, two of the patients harboring pathogenic germline ATM variants had family histories of pancreatic cancer." (PMID 31963441, 2020). "Several subsequent studies have provided additional evidence to support the role of ATM as a pancreatic cancer susceptibility gene." (PMID 31963441, 2020). "Previous studies have shown that ATM gene polymorphisms are associated with poor prognosis of patients with pancreatic cancer, acute myeloid leukemia, and colorectal cancer." (PMID 32329754, 2020). "In this study, one (0.9%) pathogenic germline ATM variant in the French-Canadian series and three (1.3%) pathogenic germline ATM variants in the Quebec pancreas cancer study series were identified, consistent with the findings of other studies." (PMID 31963441, 2020). "Metformin has been shown as a radiosensitizer in colorectal cancer by causing G2/M phase arrest, pancreatic cancer by inhibiting DNA repair to abrogate G2 phase checkpoint, esophagus cancer by activating ATM and AMPK, HCC by abrogating G2/M phase arrest." (PMID 31470817, 2019). "On the other hand, other studies indicated that ATM deficiency increases the proportion of chromosomal alterations in pancreatic cancer." (PMID 31480737, 2019). "Germline heterozygous ATM (Ataxia Telangiectasia Mutated) mutations have been observed in families with hereditary pancreatic cancer, which further links the DNA damage machinery to pancreatic cancer." (PMID 31889908, 2019). "Four (6.8%) of the 59 patients referred based on personal history of pancreatic cancer were discovered to have a pathogenic variant, and an apparently mosaic pathogenic variant in the ATM gene was detected in a fifth patient." (PMID 30186770, 2018). "More recently, mutations in Ataxia Telangiectasia Mutated (ATM) have been identified in patients with familial pancreatic cancer." (PMID 29463243, 2018). "Germline mutations in ATM (encoding the DNA-damage signaling kinase, ataxia-telangiectasia-mutated) increase Familial Pancreatic Cancer (FPC) susceptibility, and ATM somatic mutations have been identified in resected human pancreatic tumors." (PMID 28894253, 2017). "Instead, they concluded that ATM deficiency enhances pancreatic tumor potential by increasing EMT and BMP4 signaling in precancerous lesions." (PMID 28894253, 2017). "In conclusion, these novel results demonstrate that ATM deficiency confers a vulnerability (radiosensitivity) to pancreatic cancer cells that can be exploited therapeutically." (PMID 28894253, 2017).
pancreatic cancer (continued). "In contrast, cells expressing γH2AX were noticed in focal areas of 1 tumor specimen from a patient with a heterozygous ATM germline inactivating mutation and in large areas of 1 human pancreatic tumor that carried homozygous ATM somatic inactivating mutations." (PMID 28894253, 2017). "These collective SKY results conclusively demonstrate that ATM-deficiency increases chromosomal instability in KrasG12D-induced pancreatic tumors." (PMID 28894253, 2017). "We show that partial or total ATM deficiency cooperates with KrasG12D to promote highly metastatic pancreatic cancer." (PMID 28894253, 2017). "To further understand how ATM loss accelerates the formation of metastatic pancreatic tumors, we established low-passage cell cultures from primary PDACs and liver metastases of all 3 genotypes using published methods." (PMID 28894253, 2017). "More importantly, ATM deficiency also renders murine pancreatic tumors highly sensitive to radiation." (PMID 28894253, 2017). "First, we show that partial or total ATM deficiency cooperates with oncogenic Kras to promote highly metastatic murine pancreatic cancer." (PMID 28894253, 2017). "A second study identified loss of ATM phosphorylation on serine-1981 in 54 of 133 (41%) of pancreatic cancers and this also associated with worse overall survival." (PMID 27259260, 2016). "ATM mutations are found in lymphoid tumors, pancreatic cancers, as well as 7% of lung adenocarcinomas." (PMID 26517239, 2015). "ATM heterozygous mutations have been identified by genome-wide sequencing analysis in the germline of nearly 170 patients with history of pancreatic cancer posing ATM as a new potential target gene for predisposition of pancreatic ductal adenocarcinoma." (PMID 25247188, 2014). "It was reported that carrying pathogenic variants of ATM increase risk of pancreatic cancer." (PMID 39972282, 2025). "Similarly, heterozygous carriers of ATM mutations also have an increased risk of pancreatic cancer, and ATM mutations have been observed in approximately 5% of sporadic cases of PDAC." (PMID 40723241, 2025). "The ASGE recommends screening for pancreatic cancer starting at age 50 or in patients with an ATM mutation and first- or second-degree relatives with a pancreatic cancer history 10 years younger than the youngest relative with pancreatic cancer, which is similar to the AGA and CAPS." (PMID 39200847, 2024). "Additionally, loss of phosphorylated ATM is associated with a poor prognosis in patients with pancreatic cancer." (PMID 37674118, 2023). "The frequency of ATM mutations in pancreatic cancers and the critical role of the kinase in DDR and repair could form the basis for therapeutic targeting in pancreatic cancers with such mutations." (PMID 36975505, 2023). "ATM GPV carriers are also associated with an increased risk of pancreatic cancer (odds ratio = 4.21), prostate cancer (odds ratio = 2.58), gastric cancer (odds ratio = 2.97), ovarian cancer (odds ratio = 1.57), colorectal cancer (odds ratio = 1.49), and melanoma (odds ratio = 1.46)." (PMID 35806485, 2022). "The RR for pancreatic cancer is 2.41 in individuals with the ATM germline pathogenic variant." (PMID 34476650, 2021). "Furthermore, recent studies have reported that BRCA1/2 pathogenic variants potentially contribute to FPC and that the frequency of BRCA1/2, PALB2, and ATM variants in all pancreatic cancers is 7%." (PMID 33413558, 2021).
pancreatic cancer (continued). "In addition, ATM silencing increased PD-L1 expression and increased the sensitivity of pancreatic cancer to immune checkpoint inhibition in association with increased tumoral CD8+ T cells and established immune memory." (PMID 33224881, 2020). "Somatic ATM mutations have been identified in pancreatic cancers other than PDAC." (PMID 31963441, 2020). "Utilizing tumor histomorphology and a mutation spectrum to aid in the diagnosis of pancreatic cancers driven by ATM loss is an intriguing prospect, particularly for patients with a germline ATM variant of unknown significance or equivocal somatic data." (PMID 31963441, 2020). "Germline mutations in ATM may cause increased risks in developing familial pancreatic cancer, and somatic mutations in ATM also have been reported in resected numerous sporadic human pancreatic cancer." (PMID 31480737, 2019). "Furthermore, FBXW7 is significantly co-mutated with KRAS in colon cancer and ATM is significantly co-mutated with KRAS in pancreatic cancer." (PMID 31748650, 2019). "The exome sequencing of a large set of patients with familial pancreatic cancer demonstrated that inherited pancreatic cancer is highly heterogeneous: in these patients, germline mutations of ATM, BRCA2, CDKN2A and PALB2 are observed, all elevating risk of developing pancreatic cancer." (PMID 29156578, 2017). "Curcumin, a component of turmeric, derived from the rhizomes of Curcuma longa inhibits proliferation of human pancreatic cancer cells by activation of Ataxia telangiectasia mutated (ATM)/checkpoint kinase 1 (ChK1)/Cdc25C, blocking cyclin B1/Cdk1 activity and arresting cells at G2/M check point." (PMID 28946660, 2017). "Moreover, our SKY results strongly indicate that the primary driver of metastasis in ATM-deficient pancreatic tumors is chromosomal instability." (PMID 28894253, 2017). "Importantly, a deficiency of the serine/threonine ATM increases genomic instability and metastatic potential of a mouse model of pancreatic cancer." (PMID 29156578, 2017). "Furthermore, deep-sequencing methods also identified deleterious mutations in ATM in human pancreatic tumors classified as ‘genetically unstable’12." (PMID 28894253, 2017). "Two partial responses occurred in patients with pancreatic cancer and ataxia telangiectasia mutated (ATM) alterations: 32% decrease in an ATM E11828/ATM K1109* tumor lasting 15.8 months and 57% decrease in an ATM R3008H/germline ATM R1882* tumor lasting 13.6 months." (PMID 41160399, 2025). "Our finding in this study on the critical role of APE2 in the ATR DDR pathway in pancreatic cancer cells provides vital knowledge for future translational studies targeting APE2 functions in various mice models with different genetic backgrounds such as deficiency of ATM or BRCA1/2." (PMID 34796173, 2021). "Homozygous germline alterations in the ATM gene result in ataxia telangiectasia syndrome, which is characterized by a variety of pathological manifestations, including an increased predisposition for several cancer forms, such as breast, colorectal, gastric, and pancreatic cancers." (PMID 32708810, 2020). "However, a report that loss of ATM accelerate EMT in pancreatic cancer." (PMID 30961670, 2019). "Treatment with the PARP inhibitor olaparib provided a significant benefit over standard therapy in patients with a BRCA GV and metastatic breast or pancreatic cancer, and a high response rate in patients with ATM GVs and metastatic prostate cancer." (PMID 41546701, 2026). "The most common mutations were found in the BRCA1, BRCA2, ATM, PALB2, and CDKN2A genes, further highlighting the involvement of DDR-related genes in pancreatic cancer." (PMID 41155399, 2025).